PAK1 (p21 (RAC1) activated kinase 1)
Diseases named in the same sentence as PAK1 in open-access papers (continued):
Sharing a sentence is not in itself a finding about the gene and the disease.
cancer (continued). "The conclusion is that PAK1 inhibition could be a favorable strategy for NF-κB-dependent and apoptosis-resistant cancer treatment." (PMID 32863957, 2020). "In the light of this study, the potential in vivo efficacy of PAK1 inhibitors on cancer cells might need to be counterbalanced by possible side effects on platelet formation." (PMID 33066011, 2020). "In addition, we provide overviews on current progress and future challenges of PAK1 in cancer, hoping to provide new ideas for the diagnosis and treatment of cancer." (PMID 32863957, 2020). "In addition to the classical cancer pathways that PAK1 mainly participates in, the crosstalk between PAK1 and other pathways is also crucial for the development of cancer." (PMID 32863957, 2020). "Here, we review the function and regulation of PAK1 in cancer." (PMID 32863957, 2020). "In addition, PAK1 activation can enhance a cancer cell's resistance to BRAF inhibitors, which is mainly due to the activation of the AKT pathway." (PMID 32863957, 2020). "We found that the level of PAK1 protein is markedly higher in mammospheres than in cancer cells." (PMID 31658701, 2019). "PAK1 is involved in multiple diseases, such as cancer, mental retardation, and allergy." (PMID 30718368, 2019). "On the other hand, looking at studies on cancer stem cells, one could agree that p21 plays an important role in inducing stemness, especially through p21 activated kinases (PAK1, PAK3, and PAK4)." (PMID 31416295, 2019). "PAK1 knockdown rendered cells unresponsive to chemotactic stimuli present in the stroma, resulting in dramatically lower rates of cancer cell extravasation and metastatic colony formation compared to stimulated cancer cells." (PMID 30651600, 2019). "As PAK1 regulates cancer cell proliferation, we examined whether PAK1 regulates tumor growth using a xenograft tumor model." (PMID 31658701, 2019). "The function of PAK1 in cancer is well known, but its role in AP is still unclear." (PMID 30718368, 2019). "Furthermore, immunofluorescence analysis of MDA-MB-231 cells indicated that TG101209-treated cells expressed lower levels of nuclear PAK1 than untreated cancer cells." (PMID 31658701, 2019). "Conversely, knockdown of PAK1 by pharmacological inhibition and using short-hairpin RNA (shRNA) can significantly in hibit human cancer cell proliferation, anchorage-independent growth, migration and invasion in vitro and reduce tumor growth and metastasis in animal models." (PMID 30971268, 2019). "PAK‐1 expression is altered in various cancers, including prostate and breast." (PMID 31516713, 2019). "PAK1 and PAK4 proteins are associated with cancer tumorigenesis." (PMID 31658701, 2019). "Interestingly, increased PAK1 expression and activity have been well documented in several human cancers." (PMID 30454561, 2018). "Reportedly, Rac1 contributed to LPS-mediated p38 activation in GDIα knockdown podocytes;29 and PAK1 could activate MAPK cascades in oncogenic transformation of a variety of cancer cells." (PMID 29497040, 2018). "However, the in vitro effects are seen at concentrations that are much lower than those that have either anti-cancer or PAK-1 inhibitory effects and the in vivo effects are seen with very low doses of the compound." (PMID 29463049, 2018). "Besides biological targeting, this study shows that PAK1 dysfunction contributes to miR-494 biological functions, especially in cancer progression." (PMID 28055013, 2017). "In addition, there is evidence for the importance of the RAS-driven Rac–PAK1 effector signaling pathway in cancer development and growth." (PMID 29190895, 2017). "As a negative regulator of PAK1 (p21-activated protein kinase 1), CRIPAK is hormone sensitive and was shown to have deleterious mutations in squamous cell- and adenocarcinoma and was further confirmed in other cancer types (COSMIC: COSG57208)." (PMID 29285300, 2017).
cancer (continued). "Hyper-activation of PAK1 (p21-activated kinase 1) is frequently observed in human cancer and speculated as a target of novel anti-tumor drug." (PMID 28423593, 2017). "Thus, IPP-14 would be one of plausible anti-cancer drug candidate against PAK1 activated or Bcl-2 overexpressed cancers." (PMID 28423593, 2017). "PAK1 also contributes to therapeutic resistance of cancers of the pancreas, colon and lung, and thus may become an important target in cancer treatment." (PMID 28629331, 2017). "Finally, we tested the effect of IPP-14 on NF2-deficient cancer cell lines, because NF2 suggested as PAK1 inhibitor." (PMID 28423593, 2017). "In addition, the combined effects of PAK1 with other molecular and environmental factors likely differ among cancer types." (PMID 27027431, 2016). "In summary, the identification of MIIP as an inhibitor of Rac1 signaling by competitive binding to its downstream effector protein PAK1 has expanded our understanding of these pathways and shed light on how the cell migration pathways can be activated in cancer." (PMID 27760566, 2016). "The contradictory roles of PAK1 in cancers and AD and in cell survival and cell death suggest the possibility of PAK as a new molecular determinant whose activity could determine cell fate." (PMID 27121078, 2016). "Importantly, we show that depletion of Pak1/2 confers resistance to mitotic arrest induced by Eg5 inhibitors, highlighting the potential importance of this pathway for cancer therapy." (PMID 26078008, 2015). "We also show that depletion of Pak1/2 allows cells to escape monopolar arrest by Eg5 inhibition, highlighting the potential importance of this signalling pathway for the development of Eg5 inhibitors as cancer therapeutics." (PMID 26078008, 2015). "Furthermore, our work has established for the first time that sunitinib-induced upregulation of PAK1 kinase activity and ensuing NF-κB/IL-6 activation contributed to the accumulation of stem-like cancer cells, RCC progression and sunitinib resistance." (PMID 25675297, 2015). "After inhibiting PAK1, cancer cells rapidly underwent apoptosis." (PMID 25182632, 2014). "The oncogenic role of PAK1 has also been studied in other cancers." (PMID 25093037, 2014). "PAK1 overexpression has been documented in various malignancies including breast, colon, ovarian, lung, bladder and liver cancers." (PMID 25093037, 2014). "PAK1 expression was significantly lower in normal murine colon cells than in cancer cells." (PMID 25074784, 2014). "The development of drugs regulating the expression of Rac1, Rock1 and Pak1 may more accurately regulate actin activity which may be more beneficial in the prevention and treatment of diseases such as cancer." (PMID 23298303, 2014). "The authors also found that PAK1-induced cancer metastasis may involve activation of c-Jun NH2-terminal kinase (JNK) and phosphorylation of paxillin." (PMID 25182632, 2014). "PAK1 was recently shown to be an effective therapeutic target for cancer treatment." (PMID 25074784, 2014). "As a recognized oncogene and drugable target in many cancers, including cancers of the gastroinstestinal tract, PAK1 may not only contribute to prognosis, but may also offer new individually tailored therapeutic options for cancers." (PMID 24236193, 2013). "Furthermore, increased PAK1 expression and activity have been documented in a variety of human cancers, including breast, colon, ovarian, bladder, and brain cancers." (PMID 23950862, 2013). "Interestingly, cancer-spectrum analysis of PAK1 expression derived from an ONCOMINE dataset indicated that GEJ adenocarcinoma exhibits one of the highest PAK1 mRNA level in all 11 types of cancers (arrow)." (PMID 24236193, 2013). "We further discuss mechanisms by which inhibition of PAK1 can arrest tumor growth and promote cell apoptosis, and the types of cancers in which PAK1 inhibition may hold promise." (PMID 21653999, 2011).
cancer (continued). "Amplification or over-expression of c-MET (the receptor for HGF) is a known genetic aberration and therapeutic target in squamous NSCLC and PAK1 may be a key effector for HGF/c-MET signaling in cancer." (PMID 21653999, 2011). "Pak1 is the best-characterized downstream effector of Rac1, but it is also an important convergence point for many signaling pathways (including small GTPases and several tyrosine kinases) that are often activated in cancer cells." (PMID 20426825, 2010). "Therefore, it is likely that Rac1 and Pak1 have a role in determining the local invasive and metastatic potential of various human cancers." (PMID 20426825, 2010). "Our data suggested that Rac1 and its downstream effector Pak1 may be involved in the progression of this cancer." (PMID 20426825, 2010). "Also, an increase of Rac1 activity and Pak1 expression in the primary tumor was correlated with poorly differentiated cancer, local invasion, lymph node metastasis, LVI, and an unfavorable prognosis." (PMID 20426825, 2010). "Although much attention has been focused on roles of aberrant Pak1 activity in cancer, it has also become clear that Pak1 has critical roles in normal cell physiology and development, including mast cell function and the development of the central nervous system." (PMID 19557173, 2009). "Increased levels of PA and PI in the cancer cohort (evidenced by DESI) also have stimulatory effects on PAK1 activity through the direct binding of PLD-derived PA to PAK1 or through the involvement of PI lipids in signaling pathways that activate PAK1 (65, –67)." (PMID 41284888, 2025). "Thus, PAK1 promotes autophagosome formation in hypoxic conditions and promotes cancer progression." (PMID 36830998, 2023). "Indeed, the dual effect of Pak1 mediation on two critical hallmarks of cancer (proliferation and invasion) may represent an effective targeting that could robustly improve the response to therapies." (PMID 37258566, 2023). "Additionally, PAK1 correlates with the radiosensitivity of cancers." (PMID 35500159, 2022). "Additionally, mice lacking PAK1 had increased number of spleen T and B cells in contrast to wild type mice developing cancer in the small intestine, distal colon and rectum, indicating that PAK1 might contribute to the tumour eradication by immune cells." (PMID 33573141, 2021). "Importantly, PAK1 plays a charming role in affecting cancer cell metabolism." (PMID 32863957, 2020). "Therefore, considering the relationship between PAK1 and autophagy, the development of a therapeutic regimen targeting PAK1-autophagy might be a potential strategy for cancer treatment." (PMID 32863957, 2020). "Understanding the impact of group I PAKs and PAK1 and Rac1 to cell mechanics and invasion can lead to identification of mechanotransduction processes for future treatments to modify cell migration under certain circumstances, such as cancer metastasis or wound healing processes after tissue injury." (PMID 32047750, 2020). "In addition, considering the role of PAK in tumor immune escape, the selective use of PAK1 inhibitors or modulators (such as siRNAs, miRNAs, LncRNAs or antibody drugs) in immunotherapy may also be a candidate for adjuvant cancer treatment." (PMID 32863957, 2020). "Therefore, PAK1 targeting-inhibitors are a better option for the precise treatment of cancers." (PMID 32863957, 2020). "PAK1 acts as a hub to intelligently and accurately connect these signals, and through the most appropriate regulation, to meet the comfort, metabolic stability, immune escape, survival and further development of cancer cells under different survival conditions." (PMID 32863957, 2020). "Hence, the PAK1 has been identified as an attractive target for cancer treatment." (PMID 32863957, 2020).
cancer (continued). "Interestingly, PAK1 can enable the immune evasion to adapt to different microenvironments by regulating cancer cells' metabolisms, such as switching to oxidative phosphorylation in an aerobic environment, or switching to fatty acid oxidation in a high-lipid environment." (PMID 32863957, 2020). "Overall, PAK1 plays an important role in cancer progression, from the formation of cancer to the enhancement of the cancer cells' motor capacity, their infiltration of the circulatory system, and eventual metastasis to new tissues for survival and even cancer's drug response." (PMID 32863957, 2020). "Furthermore, PAK1 is involved in stimulating cancer cell growth, invasion, and metastasis." (PMID 29463049, 2018). "In addition, PAK1 also participates in angiogenesis in cancer." (PMID 29422044, 2018). "Since FA/BRCA deficient cells and other cells that are deficient in HR are highly susceptible to PARP small molecule inhibitors, we hypothesized that PAK inhibition could sensitize PAK1 amplified or overexpressing beast cancer cells to PARP pharmacological inhibition." (PMID 27740936, 2016). "Many studies also suggest that PAK1 may play a crucial role in cancer development." (PMID 25182632, 2014). "Therefore, PAK1 has gradually become a representative marker for cancers." (PMID 25182632, 2014). "Therefore, several oncogenic pathways may act through Pak1 to promote cancer progression, so that Pak1 protein expression had a greater impact on overall and recurrence-free survival than Rac1 activity in the present study." (PMID 20426825, 2010). "In the case of autophagy, acetylation promotes autophagy in cancer through modifications of PAK1 and FOXO1, an effect that can be reversed by inhibition of PAK1 or FOXO1." (PMID 41303712, 2025). "Consistent with previous studies, we identified PAK1 and PAK2 as selective and cancer‐specific vulnerabilities, underscoring their potential as key drivers of tumorigenesis and cancer progression." (PMID 39756822, 2025). "We initially selected three genes (PAK1, RAF1, and GRB2) based on their involvement in critical molecular signaling networks, including the MAPK signaling pathway, proteoglycans in cancer, focal adhesion, and natural killer cell-mediated cytotoxicity." (PMID 40243635, 2025). "PAK1 expression is increased in IBD and colorectal cancer (CRC), as well as several other cancer types." (PMID 40783411, 2025). "PAK1 and PAK2 emerge as critical regulators of cancer progression and survival, making them compelling targets for therapeutic development." (PMID 39756822, 2025). "Prior work has revealed that PAK1 is essential for RAS-driven cancer cells, including those of CRC, and inhibition of PAK1 sensitizes RAS- and GNAQ-mutant cells to MAPK cascade inhibitors." (PMID 41465386, 2025). "The PAK family, divided into group I (PAK1–3) and group II (PAK4–6), regulates cancer cell migration, invasion, and endothelial permeability through modulation of cytoskeletal dynamics and contractility." (PMID 41228228, 2025). "Inhibition of PAK1 diminishes PSC activation, thereby thwarting their protective effects on cancer cells, enabling lymphocytes to eradicate cancer." (PMID 40332759, 2025). "CRISPR knockout also identified PAK1 and PAK2 as strongly selective genes, underscoring their potential as cancer‐specific vulnerabilities." (PMID 39756822, 2025). "In the MAPK/Ras pathways, nine proteins were downregulated including C-Raf_pS338, MAPK_pT202_Y204, Elk1_pS383, Tau, Creb, C-Myc, JNK_pT183_Y185, c-jun_pS73, and Ets_1, while three proteins were upregulated in cancer including B-Raf_pS445, MNK1, and PAK1." (PMID 41284888, 2025). "The selective dependencies on PAK1 and PAK2, as revealed by DepMap CRISPR analysis, position these isoforms as critical components of cancer cell survival in specific contexts." (PMID 39756822, 2025). "Among PAK isoforms, group I PAKs (especially PAK1 and PAK2) are the best characterized and most deregulated in cancers." (PMID 40864802, 2025).
cancer (continued). "In this study, we have determined the effect of dual inhibition of PAK1 and PAK4 in PDA progression using knockout (KO) cancer cell lines." (PMID 38797819, 2024). "Additionally, PAK1 plays a crucial role in cancer-related angiogenesis, proliferation, and vascular remodeling; the overexpression or nuclear translocation of activated PAK1 confers a proangiogenic function to mucinous fibrosarcoma, highlighting the vulnerable PAK1/STAT5B/CSF2 regulatory axis." (PMID 39766303, 2024). "Twelve components were included in the MAPK signalling pathway, and of these, EFNA3, STMN1, PAK1, and TNF have previously been found to regulate EMT in cancer progression." (PMID 37225681, 2023). "It was reported that GRAF1 regulated the expression of CDC42, which was able to activate the PAK1/MAPK pathway and led to the migration and invasion of cancer cells." (PMID 36849460, 2023). "Hyperactivation of PAKs also supports cell survival over cell death, and the targeted depletion of PAK1, PAK2, or PAK4 in human cancer cell lines has been shown to compromise fitness and ability to survive in a variety of cancer types." (PMID 36830998, 2023). "We have reported that PAK1 inhibition increased levels of intra-tumoral CD3+, CD4+, and CD8+ T cells and decreased PD-L1 expression of cancer cells, thereby stimulating anti-tumour immunity." (PMID 38067120, 2023). "The most extensively studied members among the PAK proteins are PAK1 and PAK4, which have been found to be overexpressed in many types of cancers." (PMID 38067120, 2023). "Since the discovery of the founding PAK1 in 1994, the PAK in the cancer biology field has made a tremendous advancement in basic and preclinical PAK research." (PMID 36830998, 2023). "Among the 46 ICP genes studied, the expression of PAKs, especially PAK1, was surprisingly significantly correlated, and most were positively correlated, with ICP genes in numerous cancers." (PMID 36064705, 2022). "PAK1, which is a member of group I of the PAK family, is an important regulator of cell growth and metastatic phenotypes in cancer." (PMID 34976179, 2022). "The next question we asked ourselves was, how relevant WNK3 and the other four top inhibited targets (EIF2AK2, p38γ, PAK1, and RPS6KA3) are to cancer." (PMID 35163434, 2022). "Different mechanisms can explain the anti-cancer activity of Ivermectin, including inhibition of MDR, modulation of Akt/mTOR, and Wnt/TCF signaling pathways, inactivation of PAK-1 expression, among others." (PMID 36139522, 2022). "Frequent copy‐number aberrations were also found for important cancer genes, such as CDKN2A, KIT, MDM2, CCND1, CDK4, and PAK1, among others." (PMID 35229492, 2022). "Herein, we focused our analysis on the relationship between PAK1 expression and ICP genes in pan-cancer." (PMID 36064705, 2022). "According to reports, Myr inhibits the proliferation of various cancer cells through multiple signaling pathways, including PI3K/AKT, PAK1/MEK/ERK1/2, cyclin D1/PCNA, STAT3 and so on." (PMID 35646711, 2022). "Of note, an altered kinase signaling network involving EGFR, PDGFR, PAK1, PTK2 (FAK), PRKCD, and MAP2K2 appear to regulate the aberrant changes in the cancer cells and the TME accompanying recurrence." (PMID 35919862, 2022). "NF-kB, a transcription factor regulating inflammation, transformation, proliferation, angiogenesis, invasion, metastasis, and chemoresistance in cancer, is modulated by AKT and PAK1." (PMID 34066419, 2021). "In sum, these results explain the phenotypic change in cancer cells and indicate an inhibitory role of NDRG1 in actin reorganization and cell invasiveness via a CDC42/PAK1/Cofilin dependent pathway." (PMID 33994856, 2021). "Macrolide drugs induce cell cycle arrest, apoptosis, and autophagic death in cancer cells by regulating multiple targets and multiple signaling pathways, including WNT-TCF and PAK1-AKT-mTOR, and also play a role in reversing tumor resistance." (PMID 33996598, 2021).